KCNH2 (potassium voltage-gated channel subfamily H member 2)
Diseases named in the same sentence as KCNH2 in open-access papers (continued):
Sharing a sentence is not in itself a finding about the gene and the disease.
ventricular fibrillation (18 papers, 2012 to 2025). A disorder characterized by an electrocardiographic finding of a rapid grossly irregular ventricular rhythm with marked variability in QRS cycle length, morphology, and amplitude. "We report a 37-year-old woman with an out-of-hospital cardiac arrest caused by ventricular fibrillation due to digenic inheritance of long QT syndrome type 2 (KCNH2 gene) and type 6 (KCNE2 gene)." (PMID 31320904, 2019). "Impairment of Kv11.1 function by mutations in the KCNH2 gene or by a variety of drugs prolongs the QT interval of electrocardiograms leading to inherited and acquired type 2 long QT syndrome, increasing the risk of torsade de pointes arrhythmia, ventricular fibrillation and sudden cardiac death." (PMID 29572566, 2018). "Thus, impairment of hERG function by mutations in the KCNH2 gene or by a variety of drugs prolong the QT interval of electrocardiograms leading to inherited and acquired type 2 long-QT syndrome, increasing the risk of torsade de pointes arrhythmia, ventricular fibrillation and sudden cardiac death." (PMID 30341381, 2018). "Loss-of-function mutations in KCNH2 (HERG) cause type 2 long QT syndrome (LQT2), a condition in which the induced delayed repolarization of the heart following a heartbeat increases the risk of episodes of sudden death due to ventricular fibrillation." (PMID 24062639, 2013).
atrial fibrillation (17 papers, 2008 to 2025). A disorder characterized by an electrocardiographic finding of a supraventricular arrhythmia characterized by the replacement of consistent P waves by rapid oscillations or fibrillatory waves that vary in size, shape and timing and are accompanied by an irregular ventricular response. "The aim of this study is to investigate the potential arrhythmogenicity of three gain-of-function mutations related to atrial fibrillation—namely, KCNH2 T895M, KCNH2 T436M, and KCNE3-V17M—using modeling and simulation of the electrophysiological activity of the heart." (PMID 34135774, 2021). "Interestingly, it has been also proved that a high prevalence of variants in K+ channel encoding genes such as KCNH2 might control atrial repolarization and predispose carriers to atrial fibrillation (10.1161/circep.114.002519; 10.1093/eurheartj/ehm619)." (PMID 35846372, 2022). "The α-subunit of the myocardial IKr-channel, encoded by the KCNH2 gene, regulates both ventricular and atrial repolarization Patients with mutations in KCNH2 have a higher incidence of atrial fibrillation, although the change in ventricular repolarization may be more evident." (PMID 33224525, 2020). "The KCNE1-c.G112A (p.G38S) variant has been reported to reduce KCNH2 and KCNQ1 channel currents, enhance KCNH2 susceptibility to QT-prolonging factors, and increase the risk for LQTS, atrial fibrillation, and heart failure." (PMID 28749435, 2017). "Namely, the down-regulation of NKX2-5 indicates a deviation from cardiac tissue, accompanied by electrical remodelings, i.e., the down-regulation of KCNH2 and SCN2B, resulting in the formation of atrial fibrillation." (PMID 37445678, 2023).
heart failure (17 papers, 2011 to 2024). Inability of the heart to pump blood at an adequate rate to meet tissue metabolic requirements. "In a rabbit model of heart failure, Entinostat diminishes heart failure related prolongation of repolarization and partially restores KCNH2 and Cav1.3 expression." (PMID 30841920, 2019). "Interestingly, KCNH2 and the Ca2+ L-type channel Cav1.3 demonstrated significant changes in protein expression depending on heart failure and Entinostat treatment." (PMID 30841920, 2019).
schizophrenia (15 papers, 2010 to 2025). A major psychotic disorder characterized by abnormalities in the perception or expression of reality. "Given the possible association of CACNA1C and KCNH2 with CADF in schizophrenia, we searched the literature for significant associations with cardiac autonomic traits, QT prolongation, and/or schizophrenia." (PMID 36421807, 2022). "The evidence that subjects with a particular neuronal specific hERG isoform (KCNH2-3.1) associated with schizophrenia show a higher responsiveness to antipsychotic drugs and is a relevant example of ion channels as a therapeutic target." (PMID 33375447, 2020). "In a recent study, single nucleotide polymorphisms (SNPs) in the second intron of the KCNH2 gene on chromosome 7q36.1 were shown to be significantly associated with an increased risk for development of schizophrenia." (PMID 23029143, 2012). "The α subunit of a potassium ion channel Kv11.1 encoded by the hERG gene (KCNH2) could be involved in the molecular biological mechanism of inherent cardiac vulnerability in patients with schizophrenia for several reasons." (PMID 36421807, 2022). "In sum, our findings suggest that schizophrenia risk in KCNH2 may predispose schizophrenia patients to a well-described loss of vagal function in schizophrenia which is probably accompanied by increased sympathetic activity." (PMID 36421807, 2022). "Moreover, KCNH2-SNPs have been associated with schizophrenia, lower IQ, and lower cognitive processing speed." (PMID 36421807, 2022). "Moreover, unmedicated patients with previously identified schizophrenia risk alleles in KCNH2 rs11763131 A, rs3807373 A, rs3800779 C, rs748693 G, and 1036145 T showed increased mean HR and QTvi as compared to non-risk alleles." (PMID 36421807, 2022). "In addition, several studies have identified that the KCNH2 gene was associated with the risk of schizophrenia, including a case control study, a meta-analysis study of 1,158 schizophrenia patients and 1,704 controls." (PMID 34483996, 2021). "Several studies have reported KCNH2 as a risk gene for schizophrenia." (PMID 31543842, 2019). "In addition, several recent association studies have cited isoforms/polymorphisms of the KCNH2 gene as a risk factor for schizophrenia." (PMID 24887423, 2014). "In particular KCNH2 appears to be a strong contributor to the schizophrenia phenotype because of the presence of disease-associated SNPs in its gene together with compelling, converging evidence from (functional) brain imaging, mRNA expression and electrophysiological studies." (PMID 21629445, 2010). "A total of 5 CACNA1C SNPs and 9 KCNH2 SNPs were found and genotyped in 77 unmedicated schizophrenia patients and 144 healthy controls." (PMID 36421807, 2022). "In search of channel-encoding genes that are associated with both CADF and schizophrenia, CACNA1C and KCNH2 are promising candidates." (PMID 36421807, 2022). "Further studies are needed to investigate the potential pleiotropic role of CACNA1C and KCNH2 variation in the disease architecture of schizophrenia and CADF." (PMID 36421807, 2022). "In the present study, we provide first support for the impact of the two candidate susceptibility genes, CACNA1C and KCNH2, on CADF in schizophrenia." (PMID 36421807, 2022). "One recent study revealed that schizophrenia patients with different KCNH2 genotypes showed different responses to risperidone, a common antipsychotic drug used in the clinic." (PMID 31543842, 2019). "Intriguingly, genes encoding potassium channels have already been implicated in the aetiology of schizophrenia, such as KCNN3 and recently KCNH2." (PMID 21629445, 2010). "Hence, we suggest a potential association between CACNA1C and KCNH2 variants and CADF in schizophrenia, which needs to be replicated in larger cohorts with higher statistical power." (PMID 36421807, 2022).
schizophrenia (continued). "This includes two major findings: Unmedicated schizophrenia patients with previously identified genetic risk status for schizophrenia in CACNA1C rs2239063 A > C and five KCNH2 SNPs in strong LD demonstrate significant altered HR dynamics and QTvi compared to non-risk genotypes in these patients." (PMID 36421807, 2022). "Then, some genes such as the KCNH2 gene may play an important role in both QTc interval prolongation and schizophrenia." (PMID 34483996, 2021). "Moreover, studies on the difference in regulation and effects between KCNH7 and KCNH2 will help understand the function of the Kv channel in schizophrenia." (PMID 31543842, 2019).
glioblastoma (13 papers, 2005 to 2026). The most malignant astrocytic tumor (WHO grade IV). "Survival analysis showed that high expression of KCNH2 was associated with a poor prognosis in glioblastoma multiforme (GBM) and hepatocellular carcinoma (LIHC)." (PMID 36792990, 2023). "In the Beroukhim study, KCNH2 was significantly overexpressed in primary and secondary glioblastoma compared to normal brain and was among the top 3% and 6% overexpressed genes, respectively." (PMID 39240809, 2024). "In addition, the glioblastoma dataset of the TCGA suggests expression of further methadone target molecules, such as the cardiac voltage-gated K+ channels hERG1 (KCNH2) or nicotinic acetylcholine receptors CHRNA3/B4." (PMID 32560384, 2020).
Hypokalemia (12 papers, 2008 to 2026). An abnormally decreased potassium concentration in the blood. "It has been speculated that KCNH2 c.3140G>T may be associated with particular susceptibility towards hypokalemia or certain drugs, as it seems the case in hypokalemic patients with C-terminal mutations in HERG." (PMID 23936059, 2013). "KCNH2 is associated with potassium channel function, so patients with LQT2 are often accompanied by hypokalemia." (PMID 41560020, 2026).
acquired long QT syndrome (11 papers, 2012 to 2024). A form of long QT syndrome in which malfunction of the cardiac ion channels is caused by drugs or metabolic abnormalities. "Functional impairment of the human potassium channel Hs ERG (KCNH2) causes inherited or acquired long QT syndrome (LQTS), respectively, associated with sudden cardiac death." (PMID 35373735, 2022).
neuroblastoma (11 papers, 2013 to 2025). Neuroblastoma (NB) is the most common solid, extracranial childhood tumor. "We found that KCNH2 was most highly correlated with the 3 types of RNA modification in neuroblastoma (NB), GBM, PCPG, and OV." (PMID 36792990, 2023).
cardiomyopathy (8 papers, 2016 to 2024). A disease of the heart muscle or myocardium proper. "Five genes account for the majority of genetically explained cardiomyopathy and long QT (MYH7, MYBPC3, KCNQ1, KCNH2, SCN5A), resulting in narrower prediction confidence intervals." (PMID 33046849, 2021).
Hypoglycemia (8 papers, 2016 to 2025). A decreased concentration of glucose in the blood. "Recently, individuals with mutations in KCNQ1, encoding Kv 7.1, and KCNH2 (hERG), coding for Kv 11.1, were found to experience episodes of hyperinsulinemia and hypoglycemia after meals." (PMID 40650956, 2025).
ventricular tachycardia (8 papers, 2018 to 2023). A disorder characterized by an electrocardiographic finding of three or more consecutive complexes of ventricular origin with a rate greater than a certain threshold (100 or 120 beats per minute are commonly used). "In this study, a Chinese Han family with a KCNH2 gene mutation is reported with the proband diagnosed as LQTS because of recurrent ventricular tachycardia and syncope with QTc of 482-523ms." (PMID 37783170, 2023).
cardiac arrest (7 papers, 2019 to 2026). Cessation of breathing and/or cardiac function. "We hypothesise how this dual-system vulnerability may predispose individuals with pathogenic KCNH2 variants to both cardiac arrest and respiratory failure following seizures." (PMID 41981942, 2026).
COVID-19 (7 papers, 2020 to 2022). A disease caused by infection with severe acute respiratory syndrome coronavirus 2. "Salmeterol targets on seven non-n-COV host proteins (ADRB1, ADRB2, ADRB3, AOX1, DRD3, KCNH2, and THPO), meaning that it may not act on COVID-19 via directly targeting COV host proteins." (PMID 34539756, 2021).
catecholaminergic polymorphic ventricular tachycardia (6 papers, 2014 to 2025). Catecholaminergic polymorphic ventricular tachycardia (CPVT) is a severe genetic arrhythmogenic disorder characterized by adrenergically induced ventricular tachycardia (VT) manifesting as syncope and sudden death. "Molecular autopsies mainly include the screening of the genes known to be involved in cardiac arrhythmias, such as KCNQ1, KCNH2, and SCN5A, which are associated with long QT syndrome, and RYR2, which is associated with major catecholaminergic polymorphic ventricular tachycardia (CPVT)." (PMID 37372445, 2023). "Targeted genetic testing includes the three genes linked to long QT syndrome (LQTS), namely KCNQ1, KCNH2, and SCN5A, the latter also causing Brugada syndrome (BrS), in addition to the RYR2 gene, which is linked to catecholaminergic polymorphic ventricular tachycardia (CPVT)." (PMID 36643077, 2023).
endometrial cancer (6 papers, 2014 to 2022). Primary or metastatic malignant neoplasm involving the endometrium (mucous membrane that lines the endometrial cavity). "Statistically significant correlations were found between Kcnh2 high expression and low FIGO stages (p = 0.01), low risk endometrial cancer (p = 0.019) and infiltration less than 50% myometrial depth (p = 0.036)." (PMID 33893331, 2021).
glioma (6 papers, 2005 to 2026). A benign or malignant brain and spinal cord tumor that arises from glial cells (astrocytes, oligodendrocytes, ependymal cells). "Voltage-gated K+ channels, human ether-a-go-go-related channel (hERG, also known as Kv11.1 and encoded by the gene KCNH2), and hEAG (human ether a-go-go, Kv10.1, KCNH1) are expressed in gliomas where they have been shown to control proliferation and apoptosis." (PMID 36768856, 2023).
atrioventricular block (4 papers, 2021 to 2023). A heart block that is initiated in the atrioventricular node. "Herein, we reported a rare case of an infant who presented with high-degree autoimmune-mediated fetal atrioventricular block (AVB) with LQTS induced by a novel KCNH2 variant." (PMID 36973673, 2023).
esophageal squamous cell carcinoma (4 papers, 2019 to 2024). Esophageal squamous cell carcinoma (ESCC) is a type of esophageal carcinoma (EC) that can affect any part of the esophagus, but is usually located in the upper or middle third. "Esophageal squamous cell carcinoma (ESCC) is a highly aggressive and lethal malignancy worldwide that KCNH2 contributes to the poor prognosis of ESCC by promoting ESCC cell proliferation, migration, and invasion via TXNDC5 through PI3K and AKT phosphorylation." (PMID 38666927, 2024).
malaria (4 papers, 2017 to 2024). Malaria is a serious and sometimes fatal disease caused by a parasite that commonly infects a certain type of mosquito which feeds on humans. "Despite the positive results in fighting malaria, inhibition of the Kv11.1 channel (hERG; encoded by the KCNH2 gene) by piperaquine has raised concerns about cardiac safety." (PMID 38546223, 2024). "To assess the functional importance of genetic Kv11.1 variability and contribute toward profiling of the genetic diversity in Africa, we sequenced KCNH2 of 293 patients with uncomplicated malaria from Kollé and Bougoula Hameau in Mali who received artemisinin-based combination therapies." (PMID 38546223, 2024).
Obesity (4 papers, 2015 to 2025). Accumulation of substantial excess body fat. "The HQ group demonstrated significantly increased KcnH2 gene expression while effectively attenuating HFD‐induced obesity." (PMID 41306337, 2025). "Considering the pivotal role of incretins in appetite control and glucose metabolism, KCNH2 emerges as a promising novel target for the treatment of obesity and diabetes." (PMID 39128897, 2024). "However, we did observe a significant increase in the expression of the KCNH2 gene, which encodes a potassium voltage-gated channel involved in cardiomyocytes electrical function that is thought to be suppressed by PKD in obesity." (PMID 25798941, 2015).
lymphoma (3 papers, 2010 to 2023). A malignant (clonal) proliferation of B- lymphocytes or T- lymphocytes which involves the lymph nodes, bone marrow and/or extranodal sites. "The DNA methylation biomarker panel consisting of DSP, FZD8, KCNH2, and PPP1R14A was positive in 89% (54/61) of all lymphomas." (PMID 24260260, 2013). "However, this is, to the best of our knowledge, the first time DSP, FZD8, KCNH2, MTSS1, and PPP1R14A have been reported to be methylated in lymphoma." (PMID 24260260, 2013).
melanoma (3 papers, 2010 to 2023). A malignant, usually aggressive tumor composed of atypical, neoplastic melanocytes. "In MDA-MB-435S melanoma cells blocking of KCNH2 (HERG) potassium channel via E4301 or cisapride attenuated both proliferation and migration while activation of KCNH2 using PD118057 exhibited an opposite effect." (PMID 37529110, 2023).
diabetes (2 papers, 2024). "Repressing HERG K+ channel gene KCNH2 in mice with diabetes mellitus led to QT prolongation." (PMID 38256030, 2024).
hypothyroidism (2 papers, 2016 to 2023). Abnormally low levels of thyroid hormone. "For our novel results meeting our criteria for replication across the two datasets with a match on ICD-9 codes category, we identified a novel association between KCNH2 SNP rs1137617 and acquired hypothyroidism (ICD-9 code 244)." (PMID 27535653, 2016). "Thus, this association between KCNH2 and hypothyroidism is of potential interest." (PMID 27535653, 2016).
Sepsis (2 papers, 2021 to 2024). Sepsis is defined as life-threatening organ dysfunction caused by a dysregulated host response to infection. "As a potential cytokine effector, Kcnh2 has been proved to be associated with sepsis related inflammatory processes." (PMID 33263944, 2021). "Since sepsis could cause multiple organs dysfunction, we next analysed the damage of kidney, liver, lung and spleen stimulated by LPS among WT, Kcnh2+/‐ or NS1643, compared with control." (PMID 33263944, 2021). "Kcnh2 plays a protection role in sepsis‐induced cardiac dysfunction (SCID) via regulating FAK/AKT‐FOXO3A to block LPS‐induced myocardium apoptosis, indicating a potential effect of the potassium channels in pathophysiology of SCID." (PMID 33263944, 2021). "KCNH2 channels have also been identified as a significant effector in sepsis‐induced atrial tachyarrhythmias." (PMID 33263944, 2021). "It is meaningful that Kcnh2 involves improvement of the cardiac dysfunction in sepsis through modulating cardiomyocyte apoptosis process." (PMID 33263944, 2021). "These evidences strongly suggest that Kcnh2 may mediate AKT/FOXO3A pathways to modulate the sepsis‐induced pathological process in heart." (PMID 33263944, 2021). "Sepsis could downregulate KCNH2 level in the rat heart, as well as in LPS‐stimulated cardiomyocytes but not cardiac fibroblast." (PMID 33263944, 2021). "And growing number of work hinted that Kcnh2 also plays an important role in regulating of sepsis." (PMID 33263944, 2021). "Then, the CLP surgery was used to induce sepsis on the Kcnh2+/‐ rats." (PMID 33263944, 2021). "Activation of Kcnh2 by NS1643 exhibited opposite outcome, indicating a potential role of the molecule in heart protection during sepsis." (PMID 33263944, 2021). "Our data suggest that Kcnh2 observed reductions in heart resulted from altered processing of cardiomyocytes, which, in turn, led to downregulation of the FAK/AKT activity, increasing the expression of FOXO3A and ultimately increasing pro‐apoptosis genes BIM/PUMA expression during sepsis." (PMID 33263944, 2021). "However, the inflammatory response nearly has not significantly influenced by Kcnh2, which suggested its vital function on modulation of tolerance to sepsis in cardiomyocytes." (PMID 33263944, 2021).
type 2 diabetes (2 papers, 2020 to 2022). "Type 2 diabetes mellitus (T2DM) patients who have mutations of KCNH2 caused long QT syndrome (LQTS) and increasing insulin secretion." (PMID 36325440, 2022).